ZSCAN12P1 (zinc finger and SCAN domain containing 12 pseudogene 1)
Synonyms: ZNF187p1; dJ313I6.7; formerly ZNF305P1; ZNF96P1; ZNF96L1; ZSCAN12L1
Gene: Transcribed unprocessed pseudogene on chromosome 6 (28,092,427 to 28,092,845, forward strand). Ensembl gene ENSG00000219891.
Diseases named in the same sentence as ZSCAN12P1 in open-access papers:
ZSCAN12P1 is named in the same sentence as 3 diseases in open-access papers, as found by Europe PMC text mining. Sharing a sentence is not in itself a finding about the gene and the disease. The quoted sentences say what the papers report.
bipolar disorder (1 paper, 2021). A disorder of the brain that causes unusual shifts in mood, energy, activity levels and the ability to carry out day-to-day tasks. "We found that OCR SNPs on Chromosome 6 were not only in strong LD with schizophrenia and bipolar disorder GWAS index SNPs, but also with the most significant eQTL for three transcripts of the BTN2A1, ZSCAN12P1, and H4C13 genes (r2 with the top eQTL of between .88 and 1) in fetal brain." (PMID 34632689, 2021).
ZSCAN12P1 also shares sentences with these, for which no sentence is quoted: cardiovascular disease (1 paper); schizophrenia (1).